INS (insulin)
Diseases named in the same sentence as INS in open-access papers (continued):
Sharing a sentence is not in itself a finding about the gene and the disease.
metabolic disorders (continued). "Trans fats are linked to increased inflammation and impaired insulin signaling, raising the risk of metabolic diseases." (PMID 39458518, 2024). "SCFAs can regulate intestinal transport time, play a role in insulin response, and are closely associated with metabolic diseases." (PMID 38903525, 2024). "SB is a potential cause for the development of cardiovascular and metabolic diseases at a younger age and is related to the decline of cardiovascular and metabolic levels such as inflammation, oxidative stress, and insulin secretion." (PMID 39157520, 2024). "It is well established that similar to humans, male mice are less insulin sensitive and more susceptible to unhealthy diet-induced metabolic disorders than females." (PMID 39684610, 2024). "Interventions targeting the gut microbiota can potentially mitigate reduced glucose tolerance and insulin sensitivity associated with both central and peripheral metabolic disorders." (PMID 38674828, 2024). "Accordingly, many studies have shown that irisin has a potential role in metabolic diseases, such as diabetes and obesity, which can probably be linked to evidence of the regulation of metabolic peptides such as insulin, glucagon, and leptin." (PMID 38790648, 2024). "Larger studies are needed to investigate the mediating effect of insulin on the association between fat distribution and NPs, particularly in older populations with metabolic disease." (PMID 36905117, 2023). "Metabolic disorders in humans as well as in companion and production animals are often linked to an alteration in insulin signaling." (PMID 37002295, 2023). "As a result, the term “type 3 diabetes” has been proposed for AD, considering it a metabolic disease caused by insulin resistance and insulin-like growth factor in the brain (Čater and Hölter, 2022)." (PMID 37332343, 2023). "The IR we usually refer to is a metabolic disorder caused by damage to the insulin signaling pathway in traditional metabolic tissues (liver, skeletal muscle, and adipose tissue)." (PMID 38523869, 2023). "On the one hand, it has been proven that the same genes that are involved in the pathomechanism of oxidative stress, lipid metabolism, or insulin signaling are involved in follicle growth arrest and metabolic disorders associated with various PCOS phenotypes." (PMID 37371662, 2023). "Among them, metabolic inflammation is the hallmark of metabolic diseases, accompanied by infiltration and activation of immune cells along with increased inflammatory cytokines that impair insulin signaling and disrupt systemic metabolic homeostasis." (PMID 37762143, 2023). "For biomarkers associated with metabolic disease, median Hemoglobin A1c in this group fell by 45.0%, fasting insulin by 72%, glucose by 28%, and LP-IR by 59%, on average." (PMID 37942418, 2023). "As such, knockout of NCoR1 in mice results in increased metabolic homeostasis and improved insulin response, two hallmarks linked to a lower prevalence of metabolic disorders." (PMID 37059182, 2023). "T2DM, one of the most common metabolic disorders, is caused by a combination of two primary factors: defective insulin secretion by pancreatic β-cells and the inability of insulin-sensitive tissues to respond appropriately to insulin." (PMID 38003557, 2023). "Single-cell transcriptomics can reveal changes in gene expression that are associated with metabolic diseases, such as changes in the expression of genes involved in insulin signaling, glucose metabolism, and lipid metabolism." (PMID 37445852, 2023). "Natural compounds, notably plant extracts, have antioxidant, anti-inflammatory, and insulin-sensitizing properties and are considered to be a viable option for metabolic disorder treatment due to their low risk of side effects." (PMID 37374226, 2023). "As we know, IR, as a pathogenic driver of metabolic diseases, is defined as reduced sensitivity of target organs to the action of insulin." (PMID 38089616, 2023).
metabolic disorders (continued). "Insulin is a vital human metabolism hormone; hence, its secretion is highly regulated, and its deficiency or malfunction leads to many metabolic disorders affecting not only carbohydrate but also protein and lipid metabolic pathways." (PMID 38132873, 2023). "DM is a life-threatening disease throughout the world caused by metabolic disorders mainly due to high blood glucose because of insulin inadequate synthesis by the pancreas or insufficient insulin activity." (PMID 37089934, 2023). "A large percentage of patients demonstrated normalization of key biomarkers associated with metabolic disease at a randomly selected follow-up timepoint, including Hemoglobin A1c (47.5%), fasting glucose (49.6%), LP-IR (64.3%), and fasting insulin (39.5%)." (PMID 37942418, 2023). "On the other hand, miR-21 is closely associated with metabolic disorders, insulin sensitivity and ovarian pathological processes." (PMID 37303036, 2023). "Excess ectopic fat and visceral adipose tissue significantly determine the risk of CVD, while subcutaneous adipose tissue is linked to retained insulin sensitivity and reduces the risk of metabolic diseases." (PMID 37308932, 2023). "T2D is a metabolic disease characterized by high glucose levels in blood and caused primarily by cellular resistance to the activity of insulin." (PMID 38075911, 2023). "T2DM is a common metabolic disorders mainly caused by two mechanisms: reduced insulin secretion by pancreatic B cells or resistance of target tissues to insulin." (PMID 36882778, 2023). "DM belongs to a group of metabolic disorders that occurs due to defects in insulin secretion, insulin action, or both which cause the blood glucose to stay elevated pathologically." (PMID 37588318, 2023). "Intervention in the gut microbiota can combat the decreased glucose tolerance and insulin sensitivity linked to metabolic diseases both centrally and peripherally." (PMID 36891383, 2023). "A better ability to oxidize fat during exercise has been associated with lower metabolic disease risk in overweight sedentary men, better insulin sensitivity, and lower cardiometabolic risk in young adults." (PMID 37432153, 2023). "T2DM leads to body metabolic disorders that activate oxidative stress, abnormal protein processing, and proinflammatory cytokines, causing chronic inflammation and impaired neuronal insulin signaling in the brain." (PMID 37261264, 2023). "Our study showed a significant association of VAI and LAP with metabolic disorders (both glucose/insulin levels and lipid profiles) in PCOS women (p = 0.000)." (PMID 36837921, 2023). "High-fat diet (HFD) consumption causes various metabolic diseases, including metabolic syndrome and type 2 diabetes by developing insulin resistance and subsequently decreasing insulin production." (PMID 36725880, 2023). "DM refers to a group of metabolic disorders caused by impaired insulin secretion, malfunction of its action, or both, leading to hyperglycemia." (PMID 38132873, 2023). "In conclusion, daily supplementation with Obex® improved levels of selected markers of metabolic disease risk and increased cardiovascular protective effect, as well as insulin homeostasis, and was well tolerated and safe in overweight/obese adults." (PMID 36804035, 2023). "Increases in specific inflammatory markers such as IL-6 and TNF-α, which can alter insulin sensitivity by triggering insulin signaling pathways, appear to be associated with metabolic disorders." (PMID 37152739, 2023). "Since the ratios between M1/M2 macrophages and TH1/TH2 T cells are increased in obese WAT, the induction of an M2-macrophage phenotype in adipose tissue is linked to an improvement of this metabolic disorder by increasing insulin sensitivity." (PMID 36895792, 2023). "Recently, some studies have shown the detrimental effects of aldosterone on metabolic disorders, the mechanism of which caused by reduction of insulin secretion and function." (PMID 36117521, 2022).
metabolic disorders (continued). "Type I fibers are more insulin-sensitive and have a higher oxidative capacity than Type II fibers, and thus, are more susceptible to metabolic diseases." (PMID 36295815, 2022). "Type 2 diabetes (T2D) is a metabolic disease resulting from defects in protein, fat and carbohydrate metabolism and elevated levels of glucose in the blood that lead to impairment in insulin action and to relative deficiency in insulin secretion." (PMID 35625566, 2022). "The administration of live or pasteurized A. muciniphila was shown to negate the risk of metabolic disorders by improving glucose and insulin levels in both mice and humans." (PMID 35805168, 2022). "Akkermansia are thought to be associated with the amelioration of metabolic diseases and inflammation due to their anti-inflammatory and insulin-sensitive properties." (PMID 35721172, 2022). "T2DM is a metabolic disease characterized by peripheral insulin resistance and impaired insulin secretion caused by dysfunction of the β-cell in the pancreas." (PMID 35408734, 2022). "An earlier study had also found inverse correlations between SLC7A10 mRNA expression in subcutaneous adipose tissue and risk factors for metabolic disease (e.g., body-mass index (BMI), fasting glucose, insulin and triacylglycerols)." (PMID 36172277, 2022). "HFD usually induces elevated serum insulin and leptin levels, which are the indicators of insulin and leptin resistance, respectively, and risk factors for metabolic disorders." (PMID 36012616, 2022). "Experimental and clinical studies reveal the importance of irisin in improving insulin sensitivity, pancreatic β cell function, and the browning of white adipose tissue and associated metabolic disorders." (PMID 35883859, 2022). "Pseudoflavonifractor is a gut microbe associated with energy metabolism and insulin sensitivity, which can exacerbate metabolic disorders in diabetic patients." (PMID 35206916, 2022). "PTP1B is well established in insulin signalling and leptin signalling and has been implicated in the dysfunction of these signalling pathways observed in metabolic disease." (PMID 35562959, 2022). "Either too little or too much adipose tissue would possibly cause metabolic disorders and changes in insulin sensitivity." (PMID 36277708, 2022). "In contrast, weight issues, which predominantly contribute to further metabolic diseases, are frequently associated with insulin therapy." (PMID 35745754, 2022). "Such a diet is often linked with various metabolic disorders, increased oxidative stress, altering blood pressure, lipid profile, and reduced insulin sensitivity." (PMID 36620249, 2022). "The inverse correlation between BAT and body weight or glucose levels has made BAT an attractive target in the therapeutic management of metabolic disorders, to enhance insulin sensitivity and to lower the susceptibility for development of obesity." (PMID 36450713, 2022). "Amino acid and acylcarnitine metabolomic profiles have identified consistent patterns associated with metabolic disease and insulin sensitivity." (PMID 36002887, 2022). "The risk of developing metabolic diseases is increased in the presence of IR, and the concentration of insulin, triacylglycerols, and cholesterol is elevated before puberty and in adult life in the children of hyperandrogenic PCOS women." (PMID 36557220, 2022). "These pathological pathways are often intertwined, highlighting the complex causes and effects of impaired insulin response in metabolic diseases." (PMID 36241662, 2022). "Beyond its canonical role in maintaining energy homeostasis, insulin is a neurotrophic and neuroprotective factor important for maintaining cognitive function, prompting many researchers to consider AD as a metabolic disease linked to insulin deficiency." (PMID 36499613, 2022).
metabolic disorders (continued). "Our results of an independent contribution peripheral and central insulin sensitivity make for successful feeding regulation emphasize the necessity to control for both when treating individuals at risk for metabolic disorders." (PMID 36170006, 2022). "Adiponectin secreted from white adipose tissue is inversely associated with many risk factors involved in metabolic disorders that regulate glucose and lipid metabolism and insulin sensitivity." (PMID 35338256, 2022). "Several studies reported that higher levels of circulating CRP and insulin were associated with metabolic disorders." (PMID 35010768, 2022). "Our group and other investigators reported that high pro-NT is associated with the presence of NAFLD and metabolic diseases in adults and predicted bodyweight gain and impaired glucose–insulin metabolism in obese children." (PMID 34455471, 2022). "Among several insulin-sensitive tissues susceptible to metabolic disorders, liver is evidently recognized as an endocrine organ and target of metabolic fitness that releases hepatokines." (PMID 33668309, 2021). "To date, some PLA2s implicated in metabolic diseases were associated with altered insulin sensitivity." (PMID 33433056, 2021). "Since sex-related differences in susceptibility and progression of metabolic disorders are not yet fully understood, our aim was to examine inflammation and insulin signaling in VAT of fructose-fed female and male adult rats." (PMID 34869524, 2021). "It is possible that the fat distribution is more likely to accumulate in the viscera in males, which is more likely to cause metabolic disorders compared with subcutaneous fat, and that estrogen can improve the insulin sensitivity of adipose tissue in females." (PMID 33711964, 2021). "These metabolite disruptions predispose Mof+/− mice to developing metabolic disorders, as confirmed by physiological indicators including impaired glucose assimilation, reduced insulin secretion and elevated glycated-hemoglobin (Hb1ac) levels in these animals." (PMID 34707105, 2021). "DM is a metabolic disorder caused by insufficient secretion of insulin or defective utilization of insulin caused by a variety of etiologies." (PMID 34941155, 2021). "The reduction of insulin signals is physiological and necessary; however, any exaggeration predisposes the animals to metabolic diseases such as ketosis, fatty liver, milk fever, metritis, retained placenta or displaced abomasum." (PMID 34072724, 2021). "This metabolic disorder is caused by a lack (absolute or relative) of insulin and/or resistance to insulin that lead to chronic hyperglycemia." (PMID 34025412, 2021). "Loss of functional pancreatic islet β-cell mass leads to a deficiency in insulin secretion, leads to a deficiency in insulin secretion, the development of DM I and DM II, and metabolic disorders characterized by high blood glucose levels." (PMID 34208601, 2021). "Lower glycemic responses associated with lower insulin demands have been linked to the prevention of metabolic diseases." (PMID 33530525, 2021). "Mechanically, functional enrichment analysis showed that the poor prognosis of high-risk population was related to the metabolic disorders caused by inadequate insulin secretion, which was fueled by neuroendocrine aberration." (PMID 34090418, 2021). "Long-term insulin injection and long-term metabolic disorders cause many acute and chronic complications." (PMID 34095316, 2021). "Exercise is also associated with a lower risk of metabolic disease and improved insulin sensitivity in humans and animal models." (PMID 34046015, 2021). "DM is known as a heterogeneous set of metabolic disorders characterized by the common hyperglycemic phenotype caused by impaired insulin secretion, function, or both." (PMID 34568732, 2021).
metabolic disorders (continued). "We studied the ability of insulin, α-T and their combinations to prevent or reduce metabolic disorders caused by the activation of free radical reactions in the cerebral cortex of rats with two-vessel forebrain ischemia and subsequent reperfusion." (PMID 34769198, 2021). "More extensive research studying levels of inflammatory cytokines, inflammation-associated fatty acids, blood insulin as well as lipid level are warranted to provide more evidence on association of silage and equine metabolic disorders." (PMID 34497595, 2021). "PKD isoforms are well studied in the regulation of glucose homeostasis, insulin secretion, and lipid metabolism underlying metabolic disorders such as type 2 diabetes and obesity (summarized in other reviews)." (PMID 33807058, 2021). "Insulin dysregulation is associated with various metabolic diseases including obesity, NASH, and type 2 diabetes." (PMID 33537091, 2021). "The impairment of vascular insulin signaling has implicated in the development of macro- and microvascular diseases in hypertensive and metabolic diseases." (PMID 32851077, 2020). "The correlation between VAT and related derived indices and insulin sensitivity in the TDFS cohort are specific to a cohort of Caucasian subjects at increased risk for metabolic diseases and therefore cannot directly be transferred to the general population." (PMID 32664590, 2020). "The impaired insulin sensitivity and beta cell function can also influence the risk of lethal complications of the glucose metabolic diseases." (PMID 32514025, 2020). "DM is a metabolic disease associated with the failure to produce insulin and appropriate utilization of glucose (type 1) or insulin resistance when this hormone is produced but unable interact with its receptors (type 2)." (PMID 32630025, 2020). "The absolute or relative deficiency of insulin secretion and the decreased insulin sensitivity of target cells results in a series of metabolic disorders related to glucose, protein, fat, water, and electrolytes." (PMID 33091065, 2020). "As a global disease, DM not only is characterized by elevated blood glucose and blood lipid levels but also displays a protein metabolic disorder, which is primarily caused by the absolute or relative deficiency in insulin secretion." (PMID 32083135, 2020). "The frequency of metabolic diseases associated with defects of insulin and insulin-related pathways develop with high frequency in DS subjects." (PMID 32733190, 2020). "Altogether, metabolic disorders including glucose/lipid metabolism, oxidative stress, mitochondrial dysfunction, and protein changes caused by DM are associated with an impaired insulin signal pathway." (PMID 32083135, 2020). "MetS is characterized by the following clinical criteria: abdominal obesity, decreased peripheral tissue sensitivity to insulin, and hyperinsulinemia, which cause metabolic disorders of carbohydrates, lipids, and purines." (PMID 32963827, 2020). "Type 2 diabetes (T2D) is a metabolic disorder specified by an increased blood sugar that results from inadequate insulin function and is associated with poor insulin release in insulin-sensitive tissues." (PMID 32817750, 2020). "The studies on the PCOS exposure genes show that mostly these genes are associated with insulin sensitivity, sex hormone regulation, and metabolic disorders." (PMID 32309765, 2020). "Although improvements in insulin sensitivity are likely more relevant to clinical populations at an increased susceptibility to metabolic disease(s), even in healthy individuals, insulin sensitivity is an independent predictor of future cardiovascular disease." (PMID 32729615, 2020). "Diet and exercise are considered to be modifiable risk factors for a number of metabolic diseases, and diet-induced weight loss has been found to improve insulin sensitivity similarly in Black and White women." (PMID 32393319, 2020).